EPCAM (epithelial cell adhesion molecule)
Diseases named in the same sentence as EPCAM in open-access papers (continued):
Sharing a sentence is not in itself a finding about the gene and the disease.
pancreatic cancer (continued). "Given the ability of GSI to inhibit pancreatic tumor initiating CD44+/EpCAM+ cells in vitro, we further tested the in vivo role of GSI in a Xenograft nude mouse (NMRI-nu/nu) model." (PMID 23094026, 2012). "The metastatic behaviour of human pancreatic cancer cells to lymph nodes were investigated using a near-infrared fluorophore labelled EpCAM." (PMID 22590529, 2012). "Epithelial cell adhesion molecule is expressed on normal epithelial cells and overexpressed in a variety of epithelial carcinomas, including pancreatic cancers where heterogeneous EpCAM expression is observed." (PMID 22187035, 2012). "We found however that spheres generated from CD44+/CD24+expressing pancreatic cancer cells also expressed CD133 as well as EpCAM." (PMID 22570653, 2012). "This study demonstrates a central role of Notch signalling pathway in pancreatic cancer pathogenesis and identifies an effective approach to inhibit selectively EMT and suppress tumorigenesis by eliminating pancreatic tumor initiating CD44+/EpCAM+ cells." (PMID 23094026, 2012). "Our current study clearly demonstrated that in vivo inhibition of pancreatic tumor initiating CD44+/EpCAM+ cells by GSI resulted in a down regulation of mesenchymal cell markers and up-regulation of epithelial cell markers and can suppress tumorigenesis." (PMID 23094026, 2012). "We have used the tumor tissues from control and CDF-treated animals and here we show that CDF treatment led to decreased expression of Ki-67, EZH2, HIF-1α, VEGF, and EpCAM in pancreatic tumor remnants as assessed by immunohistochemistry." (PMID 23272057, 2012). "Based on the known roles of Notch in development and stem cell biology, we focused on effects on epithelial mesenchymal transition (EMT) and on pancreatic tumor initiating CD44+/EpCAM+ cells." (PMID 23094026, 2012). "When grown in vivo, the EpCAM expression was unaffected compared to in vitro except for the pancreatic carcinoma cell line 5072 which lost its EpCAM expression in vivo." (PMID 22590529, 2012). "Several laboratories have isolated TICs, e.g., from colorectal and pancreatic tumors, by using antibodies specific for epithelial cell adhesion molecule (EpCAM; also called ESA)." (PMID 20976159, 2010). "Normally, EpCAM is expressed at low levels in epithelial tissues; however, it is highly expressed in most precancerous tissues and almost all adenocarcinomas, including colorectal, gastric, breast, and pancreatic cancer." (PMID 39911266, 2025). "Therefore, we believe this EpCAM CAR is a promising immunotherapy to the clinic for pancreatic cancer." (PMID 41417221, 2025). "Furthermore, adoptively transferred EpCAM CAR-T cells were tolerable in two xenograft models of pancreatic cancer." (PMID 41417221, 2025). "When exposed to tumor cells, these targeted nanoparticles were specifically internalized by EpCAM-expressing tumor cells (e.g., BxPC3, a pancreatic cancer cell), while minimal uptake was observed in cells with low EpCAM expression (e.g., CCRF-CEM, a leukemia cell)." (PMID 40333451, 2025). "However, the feasibility of using EpCAM CAR-T cells in pancreatic cancer still needs to be verified." (PMID 41417221, 2025). "While EpCAM CAR-T development for pancreatic cancer remains preliminary." (PMID 41417221, 2025). "Catumaxomab can effectively eliminate CD133+/EpCAM+CSCs in malignant ascites in patients with advanced ovarian cancer, gastric cancer and pancreatic cancer, which indicates that it has potential therapeutic applications in eradicating CSCs of epithelial cancers." (PMID 38140103, 2023). "Moreover, vimentin antibodies outperformed EpCAM antibodies in isolating CTCs from all pancreatic cancer patients." (PMID 37345161, 2023). "However, the association of cancer prognosis with CTCs identified through immunofluorescence staining based on EpCAM and CK has been proven in previous studies on pancreatic cancer." (PMID 35740311, 2022).
pancreatic cancer (continued). "It has been reported that cells expressing cell surface markers CD44, CD24 and EPCAM in pancreatic tumors have the potential to promote the formation, proliferation and metastasis of cancer cells, and these cells were entitled as pancreatic cancer stem cell (CSC) by researchers." (PMID 35733218, 2022). "Besides, EpCAM has also been identified as a general exosomal biomarker in colorectal, ovarian and pancreatic cancer." (PMID 36431072, 2022). "Meanwhile, other studies have indicated that EpCAM protein exists in EVs, and EpCAM-positive EVs may be useful biomarkers in ovarian and pancreatic cancers." (PMID 34439276, 2021). "The antitumor ether lipid edelfosine induces apoptosis in CD44+CD24+EpCAM+ pancreatic cancer stem cells (CSCs) and blocks the formation of pancreatic CSC spheroids, derived from the established human pancreatic cancer cell lines as well as from pancreatic cancer patient-derived primary cultures." (PMID 34885233, 2021). "Some studies suggest that the levels of exosomal EpCAM could constitute a biomarker of ovarian and pancreatic cancers." (PMID 33343836, 2020). "However, although most pancreatic tumors are EpCAM positive (96%), EpCAM expression levels in PDAC cells are heterogeneous with only half of tumors showing strong expression in reasonable percentages of the tumor cells." (PMID 35582043, 2020). "To test whether cells had undergone dedifferentiation, we first assessed the expression of CD44 and EpCAM, as these represent the two most accepted CSC-associated markers in pancreatic cancer." (PMID 32764385, 2020). "Moreover, tumor-initiating cells (TICs) isolated from pancreatic cancer patient positive for CSCs markers EpCAM+/CD44+/CD24+ display high CAIX expression." (PMID 32560271, 2020). "Through our ELISA assay we measured levels of different exosome populations, in particular those carrying the ubiquitous CD9, CD81 and some markers already found in tumour exosomes of pancreatic cancer such as CD44v6, Tspan8, EpCAM, CD24, CXCR4, Integrins α6 and β4, CD133." (PMID 31048929, 2019). "CTC counting with CellSearch® is limited to the identification of EpCAM+ pancreatic tumor cells." (PMID 31717747, 2019). "Pancreatic cancer patients exosomes express EpCAM, whose levels change during treatment." (PMID 31048929, 2019). "FF-nPES analysis of serum EV EpCAM expression may have potential for the early diagnosis and monitoring of pancreatic tumors if results from clinical trials match our mouse model results." (PMID 31921310, 2019). "EpCAM staining revealed that both EpCAM+ and EpCAM− cells were present in the dissociated pancreatic cancer cell clumps, indicating that pancreatic cancer cells could be discriminated from stromal cells after staining for EpCAM." (PMID 30038429, 2018). "As EpCAM expression is highly variable within CTC-populations we selected three different pancreatic cancer cell lines that express different levels of EpCAM for the required spike-in experiments: Capan1 as high, BxPc3 as medium and Panc1 as low EpCAM expressing cell lines." (PMID 29156783, 2017). "EpAb2-6, which recognizes a particular epitope on EpCAM, can directly induce cancer cell death and may be a suitable basis for devising treatments for colon and pancreatic cancer." (PMID 26317650, 2015). "Interestingly, observed heterogeneous nuclear localization of EpCAM in lung and pancreatic cancer cell line cells in this study seems keeping in accordance with the similar previously published observation on thyroid tumor cells." (PMID 26718583, 2015). "The 5061 and 5072 pancreatic cancer cell lines showed medium to low EpCAM mRNA levels in vitro." (PMID 22590529, 2012). "In addition, AHP3 and 3-Cl-AHPC inhibited growth and induced apoptosis in spheres derived from the CD44+/CD24+ (CD133+/EpCAM+) stem-like cell population isolated from the pancreatic cancer cell lines." (PMID 22570653, 2012).
pancreatic cancer (continued). "We further proceeded to test the efficacy of GSI on pancreatic tumor initiating CD44+/EpCAM+ cells." (PMID 23094026, 2012). "Previous studies have shown that pancreatic cancers and pancreatic cancer cell lines contain a small segment of cell population characterized by expression of CD133 or CD44/CD24/EpCAM positivity and which can be utilized to identify this cancer stem cell population." (PMID 22570653, 2012). "Based on this prior work, we have chosen to analyze pancreatic tumor initiating CD44+/EpCAM+ cells." (PMID 23094026, 2012). "Our in vitro results clearly showed that the inhibition of Notch signalling by GSI resulted in a dose-dependent growth attenuation of human pancreatic tumor initiating CD44+/EpCAM+ cells, down regulated the Notch target Hes1 and decreased EMT-related molecules." (PMID 23094026, 2012). "Furthermore, under GSI IX treatment, decline in the growth of pancreatic tumor initiating CD44+/EpCAM+ cells was observed in vitro and in a xenograft mouse model." (PMID 23094026, 2012). "Moreover, in pancreatic cancer, EpCAM may facilitate tumor cell proliferation and migration, suggesting its involvement in the growth and metastasis of pancreatic tumors." (PMID 39184916, 2024). "We hypothesized that HIPEC, with the use of gemcitabine after cytoreductive surgery, will decrease tumor progression of pancreatic cancer by reducing the residual neoplastic volume and PaCSCs subpopulation (EpCAM+CXCR4+CD133+), improving patient survival by reducing disease recurrence." (PMID 38730669, 2024). "Moreover, vimentin antibodies outperformed EpCAM antibodies for all pancreatic cancer patients." (PMID 37345161, 2023). "More specifically for GC, while EpCAM-CAR T cells alone reduced or eliminated tumor burden but were susceptible to relapse, bispecific CAR T cells targeting EpCAM and ICAM-1 significantly prevented relapse and decreased tumor size in gastric, lung, breast, and pancreatic cancer." (PMID 38067366, 2023). "Furthermore, adoptive transfer of EpCAM CAR-T cells could significantly cause tumor regression in vivo in two xenograft mouse models of pancreatic cancer, without signs of organ damage." (PMID 41417221, 2025). "Here, we reported novel EpCAM CAR-T cells with a fully human single-chain variable fragment (scFv) and evaluated their specific cytotoxic effects in pancreatic cancer." (PMID 41417221, 2025). "Altogether, our data indicate that EpCAM CAR-T cells exhibit antitumor functions against pancreatic cancer PDOs, and further exploring the clinical benefits would be valuable to the pancreatic cancer therapy." (PMID 41417221, 2025). "Overall, EpCAM CAR-T cells (both 28 CAR and BB CAR) effectively inhibited tumor growth and completely eliminated tumors in two xenograft models of pancreatic cancer BxPC-3 and Capan-2." (PMID 41417221, 2025). "Our preclinical investigations confirm that the EpCAM CAR-T cells showed specific and potent anti-tumor immune responses against pancreatic cancer in vitro and in vivo." (PMID 41417221, 2025). "In conclusion, we designed a new EpCAM CAR with a fully human scFv and evaluated the anti-tumor potential in pancreatic cancer." (PMID 41417221, 2025). "To assess the potential of EVs as biomarkers of pancreatic cancer, we investigated the relative protein expression levels of four EV biomarkers (ITGαv, ITGβ5, GPC-1, and EpCAM) in EVs isolated from PDAC cell lines, mouse models, and patient plasma." (PMID 38902362, 2024). "All organoids established from YFP + EpCAM+ and YFP + EpCAM- cells from the pancreatic tumors of CKPY mice grew successfully." (PMID 36828915, 2023). "Gemcitabine-resistant pancreatic cancer exhibits cancer stemness, which is regulated by LOXL2 and is achieved through the regulation of EPCAM and oct4, c-myc by MAPK signaling." (PMID 37737908, 2023). "Magnetic NPs coated with EpCAM and CD52 antibodies are used as ligands to bind with targets of prostate, colon, lung, or pancreatic cancer or leukaemia." (PMID 38112935, 2023).
pancreatic cancer (continued). "BMI1, ALDH1A1, CXCR4, EpCAM, OCT-4, c-MYC, and NESTIN are cancer stemness-related markers of pancreatic cancer." (PMID 35806187, 2022). "In this study, surface marker expressions for the pancreatic cancer stem cell-like population, namely CD44, CD24, and ESA for Panc1 cells and CD44, CD133, and EpCAM in MiaPaCa2 cells were investigated." (PMID 35634239, 2022). "Using blood samples spiked with the pancreatic cancer cell line PANC–1 and staining for the tumor–cell markers EpCAM and cytokeratin, similar detection rates for the CS and ISX systems were observed at spiked cell numbers >10." (PMID 35681790, 2022). "To establish the antibody panel for 64Cu-TuBA, we selected seven antigens (EGFR, HER2, HER3, TfR, EpCAM, LAT1, and CD98), which are reportedly overexpressed in pancreatic cancer patients." (PMID 35628616, 2022). "Of the examined antibodies, those for EGFR and TfR showed relatively high binding to the pancreatic cancer cells used in this study, compared with those for HER2, HER3, EpCAM, LAT1, and CD98." (PMID 35628616, 2022). "Confocal microscopy revealed that these PANC-1 CSC pancreatic cancer spheroids were labeled with antibodies against CD44, CD24, EpCAM." (PMID 34885233, 2021). "In lung, breast, and pancreatic cancers, ZEB1 was shown to either directly or indirectly inhibit transcription of EpCAM." (PMID 34209658, 2021). "The most common CTC capture antibody is anti-epithelial cell adhesion molecules (EpCAM) CytoSorter® CTC system has been validated in BC, head and neck cancer, pancreatic cancer and lung cancer." (PMID 33987029, 2021). "These epCAM CCR8+ DNR CAR T cells were more efficacious at eliminating tumor and promoting survival in a preclinical model of pancreatic cancer than epCAM CAR T cells." (PMID 34868044, 2021). "Pancreatic cancer spheres were mechanically dissociated into single cells in a special cell disaggregation medium and sorted for CD44+CD24+EpCAM+ cells by means of flow cytometry." (PMID 34885233, 2021). "The PDACEV signature calculated as the unweighted sum of EGFR, EPCAM, MUC1, GPC1, and WNT2 signals showed an 86% sensitivity and 81% specificity in distinguishing pancreatic cancer patients from healthy controls." (PMID 33803470, 2021). "The LIM1863 CRC cell line can produce two mutually distinct populations of exosomes, one presenting A33 and the other EpCAM surface proteins, an important cancer-initiating marker in CRC and pancreatic cancer." (PMID 31737071, 2019). "EpCAM has been in use as a CSC marker in other solid tumours such as breast, colon and pancreatic cancers since 2000s37." (PMID 28959019, 2017). "Pancreatic CSCs express specific markers, including CD24, CD44, CD133, EpCAM, CXCR4, c-Met, and CD166, at levels substantially different from the bulk pancreatic cancer cells." (PMID 28845161, 2017). "In an orthotopic pancreatic tumor model, CDF also inhibited the expression of EZH2, NOTCH-1, CD44, EpCAM, and NANOG." (PMID 28611316, 2017). "To address the expression of the putative CSC markers CD24, CD44, EpCAM, CD133, and nestin in pancreatic cancer, we used three cell lines (P6B, P28B, and P34B) derived from PDAC tumor tissues and three corresponding FFPE tumor samples." (PMID 27414409, 2016). "CD44+CD24+EpCAM+, CD133+, ALDH+ are markers for prospectively identifying pancreatic cancer stem cells." (PMID 26673007, 2016). "Various forms of CEA, integrins, BRCA1, and tumor-associated glycoprotein-17 (TAG-17) are overexpressed on pancreatic tumor cells while c-MET, EpCAM, and CXCR-4 are also used as pancreatic cancer stem cell markers." (PMID 25157372, 2014).
pancreatic cancer (continued). "We compared EPCAM mRNA levels in MDA-MB231 breast and Panc-1 pancreatic cancer cell clones with stable short hairpin RNA-mediated knockdown of ZEB1 (shZEB1 clones) to that in control knockdown (shGFP) clones." (PMID 23667256, 2013). "Forced overexpression of FOXM1 led to increased self-renewal capacity of AsPC-1 human pancreatic cancer cells, which was consistent with enhanced expression of CSC cell surface markers such as CD33 and EpCAM." (PMID 24325450, 2013). "We analyzed the effect of the GSI IX on growth and epithelial plasticity of human pancreatic cancer cell lines, and on the tumorigenicity of pancreatic tumor initiating CD44+/EpCAM+ cells." (PMID 23094026, 2012). "The pancreatic cancer cell line KP3 expressed 98% CD44 positive and 34% of EpCAM positive cells, but when the markers were sorted together only 19% of cells were positive for both of the markers." (PMID 23094026, 2012). "Pancreatic cancer stem cells have been characterized by stem cell markers CD133+ and CD44+/CD24+/EpCAM+ (epithelial adhesion molecule)/ESA (epithelial specific antigen)." (PMID 22570653, 2012). "To evaluate the effects of EpCAM CAR in models closer to the naïve tumor microenvironment, we established a co-culture assay containing PDOs and engineered CAR-T cells using pleural effusion tumor metastasis sample from one patient with pancreatic cancer." (PMID 41417221, 2025). "We demonstrated that EpCAM CAR-T cells exhibited potent and specific anti-tumor activity against EpCAM positive pancreatic cancer in vitro and in vivo, without adverse effects by systematic delivery in xenograft mouse models." (PMID 41417221, 2025). "The FITC-conjugated EpCAM antibody (green), PE-conjugated CD44 antibody (red), PE-conjugated CD24 antibody (red), and PE-conjugated CD133 antibody (red) were used to characterize the pancreatic cancer stem cells." (PMID 39843495, 2025). "Align with our findings of EpCAM CAR in vivo, it has been reported that trophoblast cell surface antigen 2 (Trop2) targeting CAR-T cells injected intravenously could inhibit pancreatic tumor growth in the same BxPC-3 xenograft model." (PMID 41417221, 2025). "The goal of this study was to test the hypothesis that the combined treatment using the EpCAM-targeting Ec1–LoPE toxin and the HER3-targeting monoclonal antibody MM-121 would increase the efficacy of experimental therapy in a pancreatic cancer model." (PMID 36769161, 2023). "The results also emphasized that utilizing both epithelial (EpCAM) and mesenchymal (vimentin) antibodies with the lateral magnetophoretic microseparator significantly enhanced CTC isolation efficiency for both prostate and pancreatic cancer patients." (PMID 37345161, 2023). "In addition, sEV carrying members of the EGFR, EpCAM, HER2, MUC1, and Wnt families are also highly sensitive and specific in the diagnosis of pancreatic cancer and can be used as early biomarkers." (PMID 34980146, 2022). "EpCAM+ cancer cells (PD-L1− or TIM-3−), CD8+ T cells with either PD-1+ or TIM-3+, and CD14+CD68+CD163+TIM-3+ macrophages increased in the MPE of a patient with progressive pancreatic cancer." (PMID 36293034, 2022). "We observed positive staining of EpCAM in PANC-1 pancreatic cancer cells, but no positivity was observed in isolated DAFs." (PMID 36010660, 2022). "Thus, CD133, EpCAM, CD44, and CXCR4 are commonly used to isolate and examine the involvement of the CSC population in pancreatic cancer progression and constitute prime targets for the treatment." (PMID 33946266, 2021). "In human pancreatic cancer cells, CD44+/CD133+/EpCAM+ CSC-like cells exhibited lower levels of let-7 expression, and this suppressed let-7 expression promoted the expression of pluripotency transcription factor, such as NANOG, SOX2, SOX9, OCT4, KLF4 and c-myc, to maintain CSCs." (PMID 34572067, 2021).